AVP (arginine vasopressin)
Diseases named in the same sentence as AVP in open-access papers (continued):
Sharing a sentence is not in itself a finding about the gene and the disease.
Anxiety (134 papers, 2009 to 2026). Intense feelings of nervousness, tension, or panic often arise in response to interpersonal stresses. "OXT is an anxiolytic hormone, whereas AVP is anxiogenic, and an imbalance between these hormones has been linked to various mental disorders such as anxiety, depression, schizophrenia, and autism." (PMID 36998727, 2023). "In reference to levels of neuropeptide, arginine vasopressin enhances neural activity in the amygdala and is associated with anxiety-related behaviour." (PMID 37312550, 2023). "In the hypothalamic paraventricular nucleus, an excess of AVP caused by polymorphism was clearly linked to a severe anxiety phenotype." (PMID 36829752, 2023). "Since AVP has been implicated in the physiological stress response, studies have examined AVP’s role in generating anxiety-like behavior, which can greatly impact how animals interact socially." (PMID 36860367, 2023). "In particular, mice deleted for neural ERβ display increased anxiety- and depressive-like behaviors that are associated with reduced transcript levels of oxytocin and arginine-vasopressin in the bed nucleus of stria terminalis." (PMID 35269705, 2022). "It has been established that receptors of oxytocin (OXT) and arginine vasopressin (AVP) neuropeptides are distributed in different brain regions associated with central nervous system control of stress, anxiety and social behavior." (PMID 34805562, 2021). "These extra-neurohypophyseal projections of PVN AVP cells have been suggested to be implicated in anxiety and stress responses." (PMID 33796071, 2021). "In general, while the central activity that mobilizes AVP appears to be associated with an increase in surveillance, anxiety, excitation and activation, OXT has behavioral and neural effects related to anxiety reduction, relaxing, growth and restauration." (PMID 34805562, 2021). "Rodents in which AVP deficiency was observed exhibited reduced depressive and anxiety-like behavior." (PMID 34679364, 2021). "We are aware of two studies investigating relationships between AVP and behavior in dogs, both of which revealed positive associations with anxiety or aggression." (PMID 28979224, 2017). "AVP overexpression in the extreme anxiety model was caused by a SNP A (−1276) G in the promoter of the AVP gene, reducing the binding of a transcriptional repressor." (PMID 25086452, 2014). "For example, the rats showing low trait anxiety represent maternal neglect underlined by reduced AVP levels in their hypothalamus." (PMID 24550698, 2014). "Social behaviors and emotional states typically associated with AVP include pair-bond formation, courtship, aggression, fear and anxiety, and increased vigilance and arousal." (PMID 24151474, 2013). "Individual variations in the expression of AVP also underlie the expression of anxiety related behaviors in rodents." (PMID 22615973, 2012). "Furthermore, these animals display decreased levels of key neuropeptides such as OXT, orexin, and AVP—peptides associated with anxiety-like behavior, altered energy homeostasis, and autonomic dysfunction." (PMID 41516228, 2025). "In other research worth mentioning, after the intranasal administration of arginine vasopressin, participants were less willing to take a risk in a trial when the possibility of winning was high, which is similar to responses connected with elevated anxiety." (PMID 39596113, 2024). "An increase in AVP levels and activation of the V1aR have been linked to increased anxiety in mice." (PMID 36829752, 2023). "This was somewhat unexpected, as central AVP has been implicated in the modulation of anxiety." (PMID 34978098, 2022). "The AVP (and OT) systems underlie human social cognition, with short-term effects on context-specific behavioral responses and long-term behavioral regulation (e.g., anxiety, reward)." (PMID 33477721, 2021).
Anxiety (continued). "Whereas synthetic or endogenous AVP has been shown to decrease maternal aggression in Sprague-Dawley rats, contrasting and probably anxiety-dependent effects have been described in the central amygdala of high anxiety Wistar rats, where AVP release was associated with maternal aggression." (PMID 34006875, 2021). "Given that anxiety is characterized, in part, by increased arousal, AVP actions on these two behavioral states may be linked." (PMID 31160697, 2019). "In general, AVP is associated with increased anxiety, arousal and activity, while OXT facilitates anxiety-reduction and affiliation, and imbalances in activity of both neuropeptides may be associated with mental disorders." (PMID 31417378, 2019). "Finally, intracerebral injection of AVP in animals has been linked to aggressive behavior and increased anxiety." (PMID 25853137, 2015). "Hypernatremia increases the pituitary release of AVP and OT to cause renal water reabsorption and salt excretion, but the central release of these peptides is known to affect distant forebrain and hindbrain targets that also influence anxiety." (PMID 25873866, 2015). "Injection of hypertonic saline has induced panic symptoms in patients susceptible to panic attacks suggesting AVP may play a role in the induction of panic symptoms." (PMID 25853137, 2015). "Therefore, we used different approaches to examine the possible contribution of the hypomorphic allele-driven AVP deficit to trait anxiety, including correlational analyses in HAB/F1/LAB mice and association studies in F2 animals." (PMID 19357765, 2009). "However, in both rodents and humans, the closely related neuropeptides oxytocin (OT) and vasopressin (AVP) have been associated with distinct, partly opposite roles in social behavior, as well as in stress, fear, and anxiety responsiveness following social separation." (PMID 31779267, 2019). "Thus, social as well as anxiety-related behaviors might be additional sensitive targets of risk factors altering OT and AVP." (PMID 19165396, 2009). "It significantly reduced arginine vasopressin, Self‐Rating Anxiety Scale scores, and Chinese Perceived Stress Scale scores (p < 0.01), while increasing oxytocin levels and VO2max (p < 0.05)." (PMID 41369982, 2025). "Virally induced selective manipulation of AVP neurons in the PVN can modify anxiety-like behaviour and self-grooming in both sexes and mediate social investigation only in female mice." (PMID 40858267, 2025). "We previously reported that AVP in the amygdala contributed to emotional responses and anxiety-affective-like behaviors in male rats in acute pain." (PMID 40362753, 2025). "The positive correlation between AVP and anxiety-like behaviours in the OFT, coupled with its positive correlation with aggression, paints a picture of AVP as a potential modulator of stress-related behaviours, influencing both aggression and anxiety." (PMID 40011829, 2025). "Studies have shown that changes in AVP gene expression can lead to stress-related disorders such as anxiety and depression." (PMID 40243462, 2025). "Conversely, AVP’s positive correlation with both aggression and anxiety-like behaviours underscores its modulatory role in stress-related behaviours." (PMID 40011829, 2025). "This method effectively isolates mice socially, exacerbating anxiety and depression, and affects neuropeptide levels (e.g., AVP, OXT), even in naïve mice." (PMID 38474180, 2024). "It is reasonable to postulate that, in females, the decrease in conditioning produced by AVP microinjection is influenced by other factors inherent to sex, and an effect on anxiety cannot be discarded." (PMID 39135790, 2024). "In this sense, it is reasonable to postulate that, in females, the decrease in conditioning generated by AVP microinjection is influenced by other factors inherent to gender, and an effect on anxiety cannot be discarded." (PMID 39135790, 2024).
Anxiety (continued). "On one hand, researchers indicate that oxytocin and vasopressin have some opposing effects: arginine vasopressin is likely to increase alertness, arousal, anxiety, and activation, while oxytocin reduces anxiety, leading to relaxation." (PMID 39596113, 2024). "In contrast, direct manipulations of PVN AVP cells in mice suggest that these cells normally suppress inappropriate social/emotional behavior: social investigation in females and anxiety-like behavior in males." (PMID 36860367, 2023). "The effects of AVP treatment on anxiety levels are difficult to assess due to the scarcity of available data." (PMID 36979340, 2023). "In pre-clinical studies, this compound has been permitted to validate the AVP role in the regulation of fear and anxiety in humans." (PMID 36998727, 2023). "Specifically, the OT/AVP impact on anxiety- or depressive-like behaviors (as indicators of emotional states), memory performance and locomotor effects needs to be highlighted." (PMID 36979340, 2023). "AVP has multiple functions in the cerebrum involving social behaviors, stress, and anxiety responses, and all of these are found to be related to alcohol misuse." (PMID 37398582, 2023). "What is more, the neuropeptide arginine vasopressin (AVP) also innervates the CeA and dRN and influences 5-HT activity along with anxiety." (PMID 37064300, 2023). "Via these connections and V1A receptors, AVP has been demonstrated to indirectly influence 5-HT activity as well as anxiety and stress coping." (PMID 37064300, 2023). "In particular, an increased salivary AVP level was detected immediately after separation-induced social stress in dogs diagnosed with anxiety-related SRPs compared to unaffected dogs." (PMID 35953963, 2022). "For example, prairie voles that are socially isolated after weaning show increased anxiety-like behavior, and brain tissue analyses reported increased mRNA expression of OT, AVP, corticotropin-releasing factor (CRF) and TH in the PVN." (PMID 36247729, 2022). "The overexpression of AVP in the PVN induced depression-like behavior in a rat model of anxiety, which was normalized by long-term treatment with the antidepressant paroxetine." (PMID 36430254, 2022). "Nevertheless, losing their partner still induced anxiety and depressive-like behaviors, and altered density of OT, AVP, and corticotrophin-releasing hormone positive cells in the PVN were detected." (PMID 36247729, 2022). "Studies have demonstrated alterations of classical neurotransmitters, such as GABA in relation to anxiety, and neuromodulatory peptides, such as arginine vasopressin and substance P in relation to aggression." (PMID 36281632, 2022). "The neuropeptide vasopressin (AVP) has been shown to augment anxiety and fear expression and to increase the neuroendocrine stress response following social separation in both rodents and humans." (PMID 35953963, 2022). "Several studies have shown the importance of OT and AVP on stress, anxiety, cognition, and social behavior in both preclinical and clinical settings." (PMID 34769501, 2021). "AVP is also released into the central nervous system (CNS) and acts as neuromodulator that affects many psychiatry functions, such as anxiety, social behavior, learning, and memory." (PMID 34070416, 2021). "Many research studies supported the observation that the AVP level is positively correlated with the manifestation of anxiety symptoms in adulthood." (PMID 33808441, 2021). "AVP is predominantly involves in male social behavior (e.g. aggression, scent marking, courtship), stress adaptation and anxiety, and maternal nurturing behavior (Burbach, Young and Russell, 2006; Lim and Young, 2006)." (PMID 36246514, 2021). "Because of the close relationship between anxiety and depression, AVP is thought to mediate both diseases." (PMID 34679364, 2021). "Our previous study indicated the contribution of AVP to anxiety and the emission of MS-USV using a genetic model: the natural AVP-deficient Brattleboro strain." (PMID 33808441, 2021).
Anxiety (continued). "The peptides AVP and OT are key hormones in the peripheral system and in the brain with largely opposite roles in modulating stress, anxiety, and social behaviors." (PMID 34512251, 2021). "This theory increased the interest in AVP for developing therapy against stress-related disorder, especially anxiety and depression targeting the V1b receptor." (PMID 34502322, 2021). "In AVP-exposed male offspring, we found increased sociability and increased anxiety-like behavior on the elevated plus maze, while in females procedural learning was disrupted." (PMID 33510137, 2021). "Such anxiety regulating the action of AVP can explain the results for trust behavior observed in this study." (PMID 31354450, 2019). "In fact, prenatal or postnatal administration of genistein in rodents interferes with anxiety-related behaviors and with neuronal nitric oxide synthase (nNOS), vasopressin (AVP) and kisspeptin (Kiss) pathways in the adult." (PMID 31109056, 2019). "These cell groups also project to the lateral septum, where AVP modulates anxiety-like behavior on the elevated plus maze." (PMID 31160697, 2019). "Previous studies showed that AVP neurons in the hypothalamus are axon-projected to the amygdala, which is the center of anxiety and fear processing." (PMID 31354450, 2019). "Arginine vasopressin has been suggested to contribute to anxiety and depression, and the renin–angiotensin–aldosterone system via angiotensin 1a receptors, has a role in a stress response that involves the hypothalamic–pituitary–adrenal axis." (PMID 31450591, 2019). "In particular, OT has been found to attenuate anxiety, central fear responses, and neuroendocrine reactivity, while stimulation of the AVP system has been shown to lead to augmented anxiety and fear expression and increased neuroendocrine stress response." (PMID 31779267, 2019). "In other studies, employing rats selected for low or high anxiety, the release of AVP in the septum is considerably lower in the much more aggressive low anxiety rats than in the less aggressive, high anxiety rats." (PMID 29184535, 2017). "In men, intranasal AVP increases the amygdala response to emotional scenes, consistent with increased self-reported anxiety." (PMID 28871239, 2017). "In contrast, AVP activates the hypothalamic-pituitary-adrenal (HPA) axis, and is more strongly linked to anxiety and aggression." (PMID 28979224, 2017). "Historically, AVP has been noted to have effects antagonistic to those of OT, increasing anxiety, depression, and stress responses." (PMID 29021768, 2017). "V1a receptors in the brain moderate anxiety producing responses to arginine vasopressin, whilst their presence in the vasculature help moderate the pressor actions of arginine vasopressin through a phospholipase C-mediated pathway." (PMID 29262666, 2017). "Both maternal AVP and OXT are effective at preventing social stress-induced increases in self-directed measures of anxiety, and AVP is particularly effective at preventing impairments in overall social contact." (PMID 28018290, 2016). "CSS offspring also displayed increased perseverative and anxiety behavior, impaired social behavior, and behavior-specific responses to both maternal AVP and OXT treatment." (PMID 28018290, 2016). "As AVP has been understudied in the context of anxiety (although the first evidence points toward such an association ) so far, we tested for a link between rs11174811 and the BIS, as measured by both the Reuter and Montag and the Carver and White scale." (PMID 25852497, 2015). "Activation of the AVP-magnocells modifies significantly the conditioned anxiety state and spatial learning." (PMID 26500509, 2015). "For instance, AVP overexpression was observed in the paraventricular nucleus of the hypothalamus (PVN) of rat models with extreme anxiety and in stressed or depressed rats." (PMID 25086452, 2014).
Anxiety (continued). "The most significant implication of the gender differences in the effects of central AVP is in the development of novel treatments for depression and anxiety." (PMID 24349762, 2012). "The current conclusions support the earlier work on AVP and maternal behavior and extend the application of these findings to an ethologically relevant model of postpartum depression and anxiety." (PMID 24349762, 2012). "Growing evidence points to vasopressin (AVP) as a social behavior regulator modulating various memory processes and involved in pathologies such as mood disorders, anxiety and depression." (PMID 23236353, 2012). "Arginine vasopressin regulates urine osmolarity as well as social behavior, pairing, brain edema, and low anxiety-related behavior." (PMID 23675216, 2011). "Preclinical studies, including findings from the HAB/LAB rat model and voles, as well as clinical observations support a direct involvement of centrally released AVP in anxiety/depression-like behaviors and disorders." (PMID 19357765, 2009). "Furthermore, the differential effects of AVP and corticosterone on both aggression and anxiety-like behaviours highlight the nuanced and context-dependent roles these markers play in modulating behavioural responses." (PMID 40011829, 2025). "Interestingly, even with music playing backward as an acute stressor, concentrations of testosterone, oxytocin, AVP, and aldosterone were slightly increased accompanied by increased anxiety." (PMID 38915776, 2024). "Hypersecretion of AVP and consequent increase in plasma AVP concentration may lead to depression, including endogenous or major depressive disorder and anxiety due to HPA disorder and following hypercortisolemia." (PMID 36768443, 2023). "It is proposed that, if AVP’s central release patterns reach an upper limit of a continuum, “normal” anxiety might progress to pathological anxiety, with AVP aiding in this psychopathological process." (PMID 36829752, 2023). "In addition to its role in the regulation of general stress physiology, several lines of evidence link PVN AVP cells to behavioral responses to social stress and the regulation of anxiety-related behaviors." (PMID 36860367, 2023). "Additionally, AVP contributes to avoidance and anxiety-like behavior in response to stressful situations." (PMID 36860367, 2023). "To further establish the connection between CRF and AVP signaling pathways and KP-13′s anxiety- and HPA axis-stimulating effect, we conducted a set of experiments in which, before the administration of KP-13, a pretreatment with non-selective CRFR or a V1R antagonist was performed." (PMID 37760887, 2023). "Research on arginine vasopressin and oxytocin illustrated that these matters could activate the same neuro system in both sexes but produce anxiety only for males." (PMID 37717011, 2023). "In addition to social behavior, PVN AVP cells contribute to sexually differentiated aspects of anxiety-like behavior." (PMID 36860367, 2023). "Taking these results together with that of the qPCR and the ELISA, the upregulation of AVP signaling in the amygdala and the downregulation of V1aR in the hippocampus might be involved in the anxiety-like behavior induced by the icv administration of KP-13." (PMID 37760887, 2023). "AVP seems to be involved in daily anxiety-related behavior, as well as anxiety disorders." (PMID 36829752, 2023). "For example, people with the SS genotype in AVPR1A RS3 may have exhibited AIA because of the strong effects of arginine vasopressin, which arouses anxiety in social situations, such as when there are reputation concerns." (PMID 37312550, 2023). "Since AVP plays a larger role in the regulation of male anxiety-like behavior, this system may influence how males interact with conspecifics, coping strategies, and social memory formation." (PMID 36860367, 2023).